LAG3 (lymphocyte activating 3)
Diseases named in the same sentence as LAG3 in open-access papers (continued):
Sharing a sentence is not in itself a finding about the gene and the disease.
atherosclerosis (8 papers, 2022 to 2025). A disease characterized by the build-up of fatty material and calcium deposition in the arterial wall resulting in partial or complete occlusion of the arterial lumen. "Instances of atherosclerosis or CAD associated with anti-LAG-3 therapy haven’t been documented in clinical trials." (PMID 38375475, 2024). "The development and progression of atherosclerosis have been found to be exacerbated by these inhibitors, while the role of LAG-3 in cardiotoxicity is still under investigation." (PMID 40255399, 2025). "The expression of GITR, TIM-3, LAG-3 and BTLA on T cells was also examined, as these checkpoints have previously been implicated in atherosclerosis." (PMID 40761788, 2025). "Specifically, substantial foundational cellular and animal studies indicate that the immune checkpoint proteins such as CTLA-4, PD-1, PD-L1, and LAG-3 serve as crucial negative regulators of atherosclerosis." (PMID 38375475, 2024). "LAG-3 also appears to play a regulatory role in atherosclerosis development." (PMID 41009661, 2025). "Summary of mouse models of atherosclerosis induced by LAG-3, TIM-3, and CD47 pathway inhibition." (PMID 40821806, 2025). "Several preclinical studies suggest that the CTLA-4, PD-1/PD-L1, and LAG-3 pathways play a protective role in atherogenesis, whereas their blockade may contribute to atherosclerosis progression." (PMID 41009661, 2025). "However, the inhibition of LAG-3, TIM-3, and TIGIT also carries the risk of promoting the development of atherosclerosis." (PMID 40821806, 2025). "LAG-3 could therefore be an important regulator of T cell activation in atherosclerosis." (PMID 40761788, 2025). "Clinical studies have shown that immune checkpoint LAG-3 has not been found to be correlated with cardiac complications like atherosclerosis, and coronary heart disease, because of which the FDA has approved them for anti-tumor therapy." (PMID 40255399, 2025). "Therefore, future research needs to explore the pathophysiological mechanism of LAG3 in immune cells in both CAD and atherosclerosis." (PMID 36247429, 2022). "Atherosclerosis or coronary heart disease (CAD) cases have not been reported for anti-LAG-3 therapy in clinical trials." (PMID 36263134, 2022).
breast tumor (8 papers, 2017 to 2024). "We have shown that upregulation of PD-1, CTLA-4 and LAG-3 in breast tumor tissues is associated with low enrichment of repressive histones, H3K9me3 and H3K27me3, in their promoter regions." (PMID 32760400, 2020). "More importantly, our study suggests that the presence of LAG-3 B cells in breast tumors could be associated with a good prognosis, as patients with higher levels of LAG-3 B cell transcripts had a longer progression-free interval (PFI)." (PMID 38773133, 2024). "The immunological checkpoint molecule LAG3 was also shown to be substantially expressed in breast tumor tissues as compared to the normal control group, according to BRCA research, which is consistent with what we discovered." (PMID 36911389, 2023). "In the same study, authors found that the promoter regions of LAG-3 genes were completely hypomethylated in breast tumor tissues, and paired-normal tissue, suggesting that DNA methylation has no role in the upregulation of these genes in BC." (PMID 32760400, 2020). "To quantify the binding intensity of H3K9me3 and H3K27me3 on the promoters of PD-1, CTLA-4, TIM-3, and LAG-3 in normal and breast tumor tissues, we performed a ChIP-qPCR analysis using H3K9me3 and H3K27me3 antibodies." (PMID 29983831, 2018). "In conclusion, our study shows that multiple immune checkpoints including PD-1, CTLA-4, TIM-3, and LAG-3 are upregulated in breast tumor tissues." (PMID 29983831, 2018). "Initially, we found that immune checkpoints including PD-1, CTLA-4, TIM-3, and LAG-3 were upregulated in breast tumor tissues." (PMID 29983831, 2018). "We first assessed the expression level of six immune checkpoints/ligands and found that PD-1, CTLA-4, TIM-3, and LAG-3 were significantly upregulated in breast tumor tissues (TT), compared with breast normal tissues (NT)." (PMID 29983831, 2018). "In opposition to the previous results, here we observed a more pronounced increase of this phenotype in the 4T1 tumor-bearing mice, which could suggest that distinct breast tumor subtypes may distinctively influence the emergence of LAG-3 + B cells." (PMID 38773133, 2024). "Immune inhibitory receptors (PD1, CTLA4, LAG3 and TIM3) were co-expressed on certain subtypes of T cells in breast tumors, and PD1 and CTLA4 were both positively correlated with CD8+ Tcm and CD8+ T cells." (PMID 32728493, 2020). "This study critically advances our knowledge of the epigenetic modifications behind the transcriptional upregulation of PD-1, CTLA-4, TIM-3, LAG-3, TIGIT, and PD-L1 in breast tumor tissues." (PMID 29983831, 2018). "In our study, we checked the expression of immune checkpoints/ligand including PD-1, CTLA-4, TIGIT, TIM-3, LAG-3, and PD-L1 and found that PD-1, CTLA-4, TIM-3, and LAG-3 were upregulated in breast tumor tissues, compared with normal tissues." (PMID 29983831, 2018).
endometrial cancer (8 papers, 2020 to 2025). Primary or metastatic malignant neoplasm involving the endometrium (mucous membrane that lines the endometrial cavity). "The co-occurrence of LAG-3+ lymphocytes and GAL-3+ tumor cells is common in endometrial cancers, especially in tumors with methylation deficiency in mismatch repair." (PMID 36077354, 2022). "LAG3 can be used as a target for immunotherapy in endometrial cancer and in conjunction with other immune checkpoints, such as PD-1." (PMID 33324448, 2020). "Additionally, molecules such as VISTA, TIM-3, and LAG3 are expressed in endometrial cancer and may serve as markers for T cell exhaustion." (PMID 40356925, 2025). "First, we included the expression profile data of all normal endometrial samples and endometrial cancer samples of TCGA and observed the expression levels of common immune checkpoints, including PDCD1, CD274 (PDL1), PDCD1LG2 (PDL2), CTLA4, LAG3, and HAVCR2." (PMID 37872211, 2023). "As previously observed, LAG-3 is co-expressed with CD8A and PD-L1 in most tumor types, and overexpression is observed in endometrial cancer as well." (PMID 36077354, 2022). "Finally, we found that LAG3 may be a potential immune checkpoint for endometrial cancer." (PMID 36589842, 2022). "However, it was observed that T cell exhaustion markers (LAG-3, TIM-3, TIGIT) and T cell inhibitors (PD-1, CTLA-4) were strongly correlated with CD8A expression in all endometrial cancers of all molecular subtypes." (PMID 36077354, 2022).
Obesity (8 papers, 2020 to 2025). Accumulation of substantial excess body fat. "Another study also reveals that obesity induces a decreased expression level of PD-1, lymphocyte-activation gene 3 (Lag3), and T cell immunoglobulin and mucin domain-3 (Tim3) in tumor-infiltrating CD8+ T cells, resulting in CD8+ T cell dysfunction." (PMID 40863244, 2025). "In each case PD-1, Tim3 and Lag3 all were significantly increased in older DIO mice providing evidence that obesity and aging together is sufficient to induce an outwardly exhaustive phenotype in T cells." (PMID 36776393, 2022). "Notably, obesity induces T-cell depletion, as evidenced by increased expression of PD-1, T cell immunoglobulin and mucin domain-3 (TIM-3), and lymphocyte activation gene-3 (LAG-3) in tumor-bearing mice with diet-induced obesity (DIO)." (PMID 39253074, 2024). "Compared with normal group, obesity group showed decreased expression of LAG3 and PD-1." (PMID 33197880, 2020). "In prior studies, we found that diet-induced obesity was associated with suppressed immune activity in the murine tumor microenvironment coincident with elevated frequencies of intra-tumoral Tregs expressing high levels of activation markers (CD44, ICOS) and suppressive mediators (PD-1, Lag3)." (PMID 36289552, 2022). "Recent findings from a study on diet‐induced obesity in mice demonstrated an increase in exhausted CD8+ tumour‐infiltrating lymphocytes (TILs) characterized by markers such as PD‐1, TIM3 and LAG3, along with a reduction in proliferating CD8+ TILs marked by Ki67 expression." (PMID 40052383, 2025). "Moreover, additional immune checkpoints, such as TIM-3, LAG-3, TIGIT, and EB4, and exhaustion markers, such as TOX, TCF-7, and Eomes, were not increased on CD8 T cells in obesity, suggesting that obesity does not accelerate classical T cell exhaustion." (PMID 35103755, 2022).
squamous cell carcinoma (8 papers, 2016 to 2024). A carcinoma arising from squamous epithelial cells. "The expression level of LAG‐3 in patients with squamous cell carcinoma was higher than that in patients with adenocarcinoma, although this difference was not significant (P > .05)." (PMID 32077528, 2020). "In studies of squamous cell carcinoma mouse models, both CD8+ and CD4+ TILs coexpressed LAG-3 and PD-1, and dual blockade of LAG-3 and PD-1 significantly suppressed tumor growth." (PMID 31681269, 2019). "The expression, in both tumor and stromal compartments, of CD4 (p = 0.024 and p = 0.008, respectively), CD8 (p = 0.044 and p = 0.008, respectively), and LAG3 (p = 0.008, in both cases) were higher in adenocarcinoma (ADC) than in squamous cells carcinoma (SCC) patients." (PMID 27463005, 2016).
α-synucleinopathies (8 papers, 2021 to 2025). "Further studies of a specific single nucleotide polymorphisms (SNPs) of the Lag3 gene and the level of soluble Lag3 that are associated with PD, support Lag3 contributing to the pathogenesis of α-synucleinopathies." (PMID 33776654, 2021). "This is increasingly relevant in the setting of synucleinopathy, where Lag3 levels and microglial activation, in general, are known to be markedly elevated." (PMID 36768798, 2023). "In summary, we report that Lag3 contributes to the pathogenesis of α-synucleinopathies, and depletion of Lag3 delays progression of neurodegenerative disease in hA53T α-syn transgenic mouse model." (PMID 33776654, 2021). "Genetic targeting of Lag3 has promise in treating α-synucleinopathies such as PD and related neurodegenerative disorders." (PMID 33776654, 2021). "In addition, LAG3 overexpression has been shown to promote α-synuclein phosphorylation at serine-129, which is one of the hallmarks of synucleinopathy in PD." (PMID 36768161, 2023). "This group hypothesised that LAG-3 and Rab5A control regional propagation of α-syn following initiation of disease in certain brain regions and that α-synucleinopathies spread in stereotypical patterns from one brain region to another." (PMID 35265944, 2022). "Here we report that Lag3 contributes to the pathogenesis of α-synucleinopathy in hA53T mice." (PMID 33776654, 2021). "Lag3 could therefore be a possible link between synucleinopathies and depression." (PMID 36768798, 2023). "Functionally, it is interesting to note that microglial Lag3 is being studied as a target for the treatment of depression and that α-syn is more highly expressed in patients with major depressive disorder, as many patients with synucleinopathies experience depressive symptoms." (PMID 36768798, 2023). "Targeting LAG3 and the LAG3-APLP1 complex offers a promising therapeutic strategy for α-synucleinopathies due to several distinct advantages." (PMID 39849529, 2025). "Using the recombinant PFFs and human A53T α-syn models, both of which drive α-synucleinopathies in mice, treatment with anti-LAG-3 antibodies or LAG-3−/− knockout resulted in reduced pathology." (PMID 35265944, 2022). "Of note, a recent controversial study with therapeutic anti-LAG-3 antibodies showed that LAG-3 is not expressed in human and murine neurons and does not modulate α-synucleinopathies." (PMID 35755891, 2022). "Importantly, the impact of LAG3 and APLP1 on cerebral vasculature suggests that targeting this complex could have benefits beyond neuron-focused approaches, addressing the broader neurovascular implications of α-synucleinopathies." (PMID 39849529, 2025). "Serum sLAG-3 levels in PD patients were significantly higher compared to healthy controls, indicating that this interaction between LAG-3 and α-syn could provide a possible target for the development of therapeutics designed to slow the progression of α-synucleinopathies." (PMID 35265944, 2022).
B-cell lymphoma (7 papers, 2016 to 2025). "In this analysis, we investigated the prevalence of the LAG3 rs870849 allele and clinical outcome in a retrospective study of a B-cell lymphoma cohort treated with current anti-CD19 CAR T-cell therapies." (PMID 41155207, 2025). "In this retrospective observational study, we analyzed treatment outcomes in B-cell lymphoma patients after CAR-T cell therapy according to the germline LAG3 gene variants (LAG3 I455hom, I455Thet, T455hom)." (PMID 41155207, 2025). "Compared to its expression in DLBCL, the expression of LAG3 is three-fold higher in HL, and the expression level of LAG3 in primary mediastinal B-cell lymphoma is similar to that in HL." (PMID 35111155, 2021). "Taken together, these results indicate that PD-1 and LAG-3 cooperatively mediate the functional exhaustion of CD4+ and CD8+ T cells and are associated with the development of B-cell lymphoma in BLV-infected cattle." (PMID 29914540, 2018). "In addition, researchers analyzed samples of patients with relapsed DLBCL after CAR-T therapy and found that the LAG-3 and PD-1 expressions on tumor-infiltrating T cells and B-cell lymphoma increased after CAR-T therapy." (PMID 38627681, 2024). "In patients with DLBCL, LAG-3 is highly expressed on CD4+ Tregs and CD8+ TILs, while its co-expression with PD-1 and TIM-3 has also been observed on certain B-cell lymphomas." (PMID 38627681, 2024).
coronary heart disease (7 papers, 2021 to 2025). "A cohort observational study showed elevated LAG-3 levels in patients with coronary heart disease, indicating that LAG-3 is a potential predictor of coronary heart disease risk." (PMID 40821806, 2025). "LAG-3 deficiency has also been associated in clinical studies with increased risk of coronary artery disease (CAD) due to Tr1 dysfunction." (PMID 34067904, 2021). "LAG-3 is a potential predictive tool as a determinant of coronary heart disease and an indicator of plasma high-density lipoprotein-cholesterol." (PMID 40255399, 2025). "Prospective cohorts have found that a decrease in plasma LAG3 protein was one of the causes of the elevation of HDL-C, which was then associated with an increased risk of coronary artery disease." (PMID 37790448, 2023). "However, an independent relationship between LAG-3 and coronary heart disease has been reported and atherosclerotic plaque expresses LAG-3 in exhausted Thymocytes." (PMID 40255399, 2025). "Additionally, in adjusted models, we examined the association of LAG3 co-expressed proteins and their association with HDL-C, coronary heart disease (CHD) and all-cause mortality." (PMID 35501457, 2022). "LAG-3 protein expression has been shown to correlate with increased coronary heart disease (CHD) and increased myocardial infarction (MI)." (PMID 34067904, 2021).
esophageal squamous cell carcinoma (7 papers, 2021 to 2025). Esophageal squamous cell carcinoma (ESCC) is a type of esophageal carcinoma (EC) that can affect any part of the esophagus, but is usually located in the upper or middle third. "Notably, even within ESCC (esophageal squamous cell carcinoma), conflicting studies have reported both favorable and unfavorable prognostic associations with LAG3 expression." (PMID 40411616, 2025). "In fact, co-expression of CD8 mitigated any negative prognostic implications of CTLA-4 or LAG-3 expression in esophageal squamous cell carcinoma patients." (PMID 39751903, 2025). "In esophageal squamous cell carcinoma (ESCC), gram-negative bacterial enrichment drives LPS accumulation, which activates the CCL3/CCL5–CCR1–MAPK axis to upregulate tumor PD-L1 while suppressing T cell proliferation/cytotoxicity, elevating PD-1/LAG-3, and reducing CD107a/IFN-γ." (PMID 41181090, 2025).
influenza (7 papers, 2012 to 2025). An acute viral infection of the respiratory tract, occurring in isolated cases, in epidemics, or in pandemics; it is caused by serologically different strains of viruses (influenzaviruses) designated A, B, and C, has a 3-day incubation period, and usually lasts for 3 to 10 days. "In agreement with these, compared to circulating Treg cells, we found that lung tissue resident Treg cells express higher levels of PD-1, TIGIT and GITR, even at the naïve state, while ICOS and LAG-3 are significantly upregulated following acute influenza infection." (PMID 36159872, 2022). "Similar to F/F/S infection, the lungs of IgMi mice with F/F/Kp infection had higher numbers of total CD8+ T cells, CD8+ TRMs, influenza-specific CD8+ T cells, and CD8+ T cells coexpressing PD-1, LAG-3, and TIM-3." (PMID 40493422, 2025). "Strikingly in the murine model of influenza infection, CD8+ T cells are the largest subset of the IL-10-producing LAG3+CD49b+ T cells in the lungs (86%), followed by Foxp3− CD4+ T cells, while Foxp3+ CD4+ are a minority." (PMID 30510554, 2018). "For both heterotypic and homotypic influenza infections, CD8+ T cells of μMT mice had higher coexpression of PD-1, LAG-3, and TIM-3 compared with WT; however, this coexpression was greater in heterotypic infection compared with homotypic infection for both WT and μMT mice." (PMID 40493422, 2025). "As such, the fact that we could not observe an induction of Lag-3, Tim-3, or Granzyme B following influenza vaccination in human Treg cells might be a consequence of the narrow window of analysis." (PMID 29951069, 2018). "In line with previous reports, expression levels for Tim-3 and LAG-3 in the blood were very low and we could not observe an induction after influenza vaccination." (PMID 29951069, 2018). "No upregulation of PD-1, LAG-3, or TIM-3 was apparent on NP-specific memory CD8+ T cells either 2 or 6 months after influenza infection, and numbers of FoxP3+ regulatory T (Treg) cells were comparable." (PMID 22965681, 2012).
tuberculosis (7 papers, 2019 to 2025). A chronic, recurrent infection caused by the bacterium Mycobacterium tuberculosis. "Targeting LAG-3 may represent a potential therapeutic target for tuberculosis." (PMID 38957797, 2024). "Analysis of the validation set data revealed reduced levels of GZMB and PRF1 in latent tuberculosis infection (LTBI) and TB patients compared to those in HI, alongside significantly elevated expression levels of the LAG-3 and IFN-γ genes in these samples." (PMID 38957797, 2024). "In another study, increased LAG-3 expression on CD4+ T cells was shown to correspond with high bacterial burden and active tuberculosis (TB) infection." (PMID 35265944, 2022). "Similarly, PD-1 on MAIT cells is expressed at a much higher level in patients with active tuberculosis compared to healthy controls; however, TIM-3 and LAG-3 are not27." (PMID 31515495, 2019).
acute myeloid leukemia (6 papers, 2021 to 2025). Acute myeloid leukemia (AML) is a group of neoplasms arising from precursor cells committed to the myeloid cell-line differentiation. "This study aimed to investigate the correlation between SNPs of two inhibitory immune checkpoint receptors PDCD1 rs2227981 and LAG3 rs12313899 and the susceptibility to acute myeloid leukemia in the Saudi population." (PMID 38792904, 2024). "The potential association between the PDCD1 rs2227981 and LAG3 rs12313899 polymorphisms and risk of acute myeloid leukemia (AML) was studied through stratified analyses based on gender and age." (PMID 38792904, 2024).